IGF1 (insulin like growth factor 1)
Diseases named in the same sentence as IGF1 in open-access papers (continued):
Sharing a sentence is not in itself a finding about the gene and the disease.
Kowarski syndrome (1 paper, 2025). "The Kowarski syndrome is clinically characterized by short stature associated with bio-inactive growth hormone, normal or slightly increased growth hormone secretion, pathologically low insulin-like growth factor 1 levels, and normal catch-up growth on growth hormone replacement therapy." (PMID 41614776, 2025). "This provides a comprehensive molecular explanation for Kowarski syndrome, where patients exhibit the paradox of short stature and low IGF-1 despite normal or elevated levels of circulating growth hormone." (PMID 41614776, 2025).
lactose intolerance (1 paper, 2023). "Other studies indicate a role of concurrent lactose intolerance of CD patients, thus reducing milk products consumption, which are known to contain the insulin-like growth factor 1 (IGF-1) that may promote tumorigenesis due to the reduction in apoptosis and angiogenesis promotion." (PMID 36833303, 2023).
language disorder (1 paper, 2024). A category of disorders characterized by an impairment in the development of an individual's language capabilities, which is in contrast to his/her non-verbal intellect. "Early speech and cognitive training have shown promising efficacy in the treatment of language disorders, as it can improve developmental quotient in affected children and increase serum levels of insulin-like growth factor-1, 25(OH)D3, and gamma-aminobutyric acid." (PMID 39470558, 2024). "This suggests that early language cognitive training may elevate the serum levels of IGF-1, 25(OH)D3, and GABA in children with language disorders." (PMID 39470558, 2024).
laryngeal carcinoma (1 paper, 2022). Carcinoma that arises from the laryngeal epithelium. "The data indirectly demonstrated the activation of PI3K‐Akt in IGF‐1‐challenged laryngeal cancer cells, ruling out the off‐target effect." (PMID 35415942, 2022). "In this study, IGF‐1 treatment activated PI3K‐Akt‐mTOR signalling pathway, enlarged the resistance to radiotherapy, and elevated glucose uptake and the expression of HIF‐1α and Glut‐1 in laryngeal cancer cells." (PMID 35415942, 2022).
Left atrial enlargement (1 paper, 2020). Increase in size of the left atrium. "A higher IGFBP/IGF-1 ratio was associated with increased E/e′ ratio, NT-proBNP levels and left atrial enlargement." (PMID 32477267, 2020). "Another anabolic key factor could be IGF-1; patients with low IGF-1levels presented left atrial enlargement that is considered one of main diastolic dysfunction criteria." (PMID 32477267, 2020).
leukopenia (1 paper, 2016). "In addition, we observed an overall decline in the physiological condition of SirT7−/− mice, including reduced circulating IGF‐1 protein, increased p16INK4 expression, altered HSC compartment, and leukopenia." (PMID 27225932, 2016).
lumbar disc degeneration (1 paper, 2017). "Serum (IGF-1) levels were lower in lumbar disc degeneration patients than those of healthy controls, and addition of IGF-1 to human NP SV40 cells induced Akt phosphorylation and then inactivated FoxO1, leading to inhibition of MMP-3 transcription." (PMID 28915718, 2017).
lupus nephritis (1 paper, 2021). Glomerulonephritis in the context of systemic lupus erythematosus. "In basic studies, the increased expression of IGFBP-2 in the outer cortical glomerulus may be associated with glomerular sclerosis and renal loss in lupus nephritis, and it may inhibit the mesangial proliferation induced by IGF-1 and enhance the extracellular matrix deposition." (PMID 35002740, 2021).
MALT lymphoma (1 paper, 2022). An indolent, extranodal type of non-Hodgkin lymphoma composed of small B-lymphocytes (centrocyte-like cells). "Focusing on explicit count expression analysis of IGF1 in our study, MALT lymphoma showed significantly lower expression of IGF1 (p < 0.011, FDR p < 0.022) when compared to NSOIs and IgG4-ROD." (PMID 36295095, 2022).
Mauriac syndrome (1 paper, 2024). A complication of poorly controlled type 1 diabetes mellitus in children characterized by linear growth impairment, glycogenic hepatopathy, and Cushingoid features. "Growth retardation is another typical finding in Mauriac syndrome, occurring because of the suppression of insulin-like growth factor 1 (IGF-1), leading to stunted growth." (PMID 39170998, 2024).
melorheostosis (1 paper, 2023). Melorheostosis is a rare connective tissue disorder characterized by a sclerosing bone dysplasia, usually limited to one side of the body (rarely bilateral), that manifests with pain, stiffness, joint contractures and deformities. "The study found that there was increased expression of certain proteins, including transforming growth factor beta (TGF-β), bone morphogenetic protein 2 (BMP-2), and insulin-like growth factor 1 (IGF-1) in the bone tissues of melorheostosis patients compared to healthy controls." (PMID 37241101, 2023).
meningitis (1 paper, 2025). A disorder characterized by acute inflammation of the meninges of the brain and/or spinal cord. "Specifically, patients with prior meningitis had lower levels of IGF-1 compared to other categories." (PMID 39787566, 2025).
metabolic myopathies (1 paper, 2013). "In fact, similarly to other metabolic myopathies, the decline of specific hormones, including IGF-1, occurring in OP might downregulate IGF-1/PI3K/Akt activity, leading to muscle atrophy." (PMID 22535191, 2013).
metastatic colorectal cancer (1 paper, 2016). "In another study, chemorefractory wild-type KRAS metastatic colorectal cancer patients harboring the IGF1 rs2946834 variant A/A genotype had a significantly higher response rate to cetuximab (50%) compared to those with the A/G genotype (0%)." (PMID 27144430, 2016).
monoclonal gammopathy of undetermined significance (1 paper, 2016). "Here we measured total IGF1, IGF2, and intact IGFBP levels in blood and bone marrow samples from MM (n = 17), monoclonal gammopathy of undetermined significance (MGUS) (n = 37), and control individuals (n = 15), using ELISA (IGFs) and 125I-IGF1 Western Ligand Blotting (IGFBPs)." (PMID 27111220, 2016).
motor neuron degeneration (1 paper, 2020). "Another group headed by Krieger identified low haematic levels of IGF1 in nmd mice; thus, these authors investigated whether the lack of insulin‐like growth factor 1 (IGF1) is involved in motor neuron degeneration in SMARD1." (PMID 31802621, 2020).
multiple system atrophy (1 paper, 2021). Multiple system atrophy (MSA) is a neurodegenerative disorder characterized by autonomic failure (cardiovascular and/or urinary), parkinsonism, cerebellar impairment and corticospinal signs with a median survival of 6-9 years. "Decreased levels of neurotrophic factors such as glial derived neurotrophic factor (GDNF), brain derived neurotrophic factor (BDNF), and insulin-like growth factor 1 (IGF1) have been identified in human brains with multiple system atrophy and in mouse models." (PMID 34512258, 2021). "Studies on mouse models and patients with multiple system atrophy showed insulin resistance in oligodendrocytes and neurons of the putamen and impairment of insulin/IGF-1 signaling." (PMID 34512258, 2021).
muscular hypertrophy (1 paper, 2014). "It is therefore of interest for future studies to examine whether this decreased circulating GH would affect muscular hypertrophy after a prolonged period of use or whether it acutely affects IGF-1 levels." (PMID 24650275, 2014).
nasopharyngeal tumour (1 paper, 2017). "In this study, IGF-1 was more weakly expressed in the majority of nasopharyngeal tumour and normal epithelial cell lines, which is in line with previous studies showing that IGF-1 expression is lower in EBV-negtive NPC cell lines." (PMID 28143425, 2017).
neck cancer (1 paper, 2015). "A separate pool of cells isolated from the head-and-neck cancer biopsy were stimulated with a growth factor cocktail of EGF/ HGF/IGF1 and demonstrated response along pAKT, pERK and pSTAT5 pathways." (PMID 25807104, 2015).
nephromegaly (1 paper, 2022). "Previous studies have shown that IGF1 overexpression causes many histopathology changes such as kidney tissue hyperplasia, renal cell proliferation, nephromegaly, mesangial expansion, and increased inflammatory cytokines." (PMID 36160448, 2022).
neuroendocrine carcinoma (1 paper, 2015). A malignant neuroendocrine neoplasm composed of cells containing secretory granules that stain positive for NSE and chromogranin. "We and others 2,3,22 have previously shown that the IGF-1 is a potent autocrine stimulus in neuroendocrine cancer cells and that neuroendocrine secretion at least in part depends on IGF-1." (PMID 25754106, 2015).
neuronal ceroid lipofuscinosis (1 paper, 2012). "It has been shown that only one-week treatment with IGF-1 partially restored interneuronal number and reduced hypertrophy in the mnd/mnd mouse model of neuronal ceroid lipofuscinosis (CLN8)." (PMID 22778966, 2012). "In summary, we have studied the biodistribution and pharmacokinetics of human IGF-1 administrated free or complexed to its natural binding protein IGFBP-3 or nanoparticles in infantile neuronal ceroid lipofuscinosis (INCL) mouse model." (PMID 22778966, 2012).
neutropenia (1 paper, 2020). A decrease in the number of neutrophils found in the blood. "The neutropenia and depressed immune function in preterm infants and pigs may be partly prevented by IGF-1 treatment, like in other life stages, but more studies are required to test this hypothesis." (PMID 33614541, 2020).
non-melanoma skin carcinoma (1 paper, 2023). "Relevant to the role of potential fibroblast senescence in non-melanoma skin cancer, oxidant-treated fibroblasts also had diminished levels of insulin-like growth factor 1 (IGF-1)." (PMID 36993812, 2023). "Recent studies have provided compelling evidence linking the aging of dermal fibroblasts, with corresponding lack of IGF-1, as playing an important role in the increased incidence of non-melanoma skin cancer (NMSC) in the elderly." (PMID 36993812, 2023).
ocular toxoplasmosis (1 paper, 2019). Ocular toxoplasmosis is an infection in the eye caused by the parasite, Toxoplasm a gondii. "Biopsy of the retinal pigment epithelium is not indicated or safe in patients with ocular toxoplasmosis, but several groups have investigated the expression of selected molecules in the ocular fluids collected from patients with ocular toxoplasmosis—VEGF, but not IGF1 or TSP1, has been measured." (PMID 31569536, 2019).
oligoarticular JIA (1 paper, 2024). "Moreover, compared with the controls, a significant (p = 0.0007) reduction in the concentration of IGF-1 in the serum of children with diagnosed oligoarticular JIA was demonstrated." (PMID 39766233, 2024).
opiate dependence (1 paper, 2015). Disorders related or resulting from abuse or mis-use of opioids. "Regarding drugs of abuse in humans, IGF-1 concentrations have been assessed in alcohol and opiate dependence." (PMID 25734326, 2015). "In contrast to alcohol, serum IGF-1 is found to be elevated in opiate dependence." (PMID 25734326, 2015).
Opportunistic infection (1 paper, 2026). An infection that is caused by a pathogen that would generally not be able to cause an infection in a host with a normal immune system. "Elevated TGF-β levels have been associated with increased risk of opportunistic infections, while early postoperative IGF-1 concentrations predict short-term survival." (PMID 42196520, 2026).
optic neuropathies (1 paper, 2022). "Experimental studies in various disease models addressed mechanisms of action and indicated modulation of neurotrophic factors (IGF-1, BDNF, CNTF, FGF-2, TNF-α) and immunomodulators (IL-10, IL-6, COX-2, NF-κB) by electrical stimulation of the eye in optic neuropathies." (PMID 35361287, 2022).
osteopetrosis (1 paper, 2025). Osteopetrosis, also known as marble bone disease, is a descriptive term that refers to a group of rare, heritable disorders of the skeleton characterized by increased bone density on radiographs. "Although there is evidence for regulation of osteoclast (OCL) function by IGF1 the complete loss of OCL and resident bone macrophages in the Csf1rko and consequent osteopetrosis is specific to the mutation." (PMID 39869647, 2025).
otitis media (1 paper, 2024). Inflammation of the anatomical structures of the middle ear, which is most often caused by an infectious process. "Chromosomal deletions, particularly in the X chromosome’s short arm, believed to be associated with CHL, and decreased levels of (IGF-1) insulin-like growth factor 1 are associated with otitis media." (PMID 39198906, 2024).
ovarian clear cell cancer (1 paper, 2015). An invasive malignant neoplasm that arises from the ovary and is characterized by a predominance of clear and hobnail malignant epithelial cells. "It inhibited the migration, increased the vasohibin-1 expression, and decreased the IGF-1 expression in not only ES-2 cells but also in another ovarian clear cell carcinoma JHOC-5 cells." (PMID 26360832, 2015). "Migracin A inhibited the migration and IGF-1 expression in not only ES-2 but also another ovarian clear cell carcinoma JHOC-5 cells." (PMID 26360832, 2015).
ovarian diseases (1 paper, 2021). "At 3 weeks postpartum, cows with ovarian diseases had greater (P < 0.05) concentrations of NEFA, and lesser concentrations of ALT, calcium, phosphorus and IGF-1 than HC cows." (PMID 34957286, 2021). "Compared to healthy controls, cows with ovarian diseases had higher (p < 0.01) NEFA and lower (P < 0.05) ALT, calcium, phosphorus and IGF-1 concentrations." (PMID 34957286, 2021). "Spearman correlation analysis showed that plasma NEFA level was positively correlated (P < 0.01) with ovarian diseases, while plasma ALT, calcium, phosphorus, progesterone, and IGF-1 levels were negatively correlated (P < 0.01)." (PMID 34957286, 2021).
ovarian endometriosis (1 paper, 2023). A non-neoplastic disorder characterized by the growth of endometrial tissue in the ovaries. "In conclusion, differential expression of IGF-1 isoforms may indicate that DIE with its associated ovarian lesions and simple ovarian endometriosis should be considered as two forms of the disease developing under different molecular pathways." (PMID 38275748, 2023). "Our results are consistent with our primary hypothesis that differential expression of IGF-1 isoforms may indicate that DIE with its associated ovarian lesions and simple ovarian endometriosis should be considered as two forms of the disease developing under different molecular pathways." (PMID 38275748, 2023).
Ovarian Hyperandrogenism (1 paper, 2022). Increased production of androgens by the ovaries. "Similar inabilities to induce ovarian hyperandrogenism, however, have arisen when exogenous insulin-like growth factor-1 (IGF-1) was administered." (PMID 35269778, 2022). "Chronic (22 days) administration of excessive doses of recombinant human IGF-1 (240 micrograms/kg/day) to normal, adult female rhesus monkeys failed to induce ovarian hyperandrogenism." (PMID 35269778, 2022).
ovarian hyperstimulation syndrome (1 paper, 2020). A complication of ovulation induction in infertility treatment. "A more recent, second study from the Cornell-Weill Institute in New York examined Day-2 IGF-1 serum levels in 184 women undergoing IVF and found those with levels >72 ng/mL (equivalent to 9.4 nmol/L) had a significantly higher risk of developing ovarian hyperstimulation syndrome." (PMID 32933040, 2020).
ovarian serous carcinoma (1 paper, 2024). "A positive correlation between RAGE and IGF1 expression was also observed in ovarian serous carcinoma, suggesting that the RAGE and IGF1 levels may control the metastatic potential of this tumor." (PMID 38892104, 2024).
Pain (1 paper, 2014). An unpleasant sensory and emotional experience associated with actual or potential tissue damage, or described in terms of such damage. "MiR124 is an especially important candidate, as it is involved in the regulation of both BDNF and IGF-1, is sensitive to uncontrollable intermittent tailshock, and has been shown to inhibit nociceptive behavior associated with neuropathic pain." (PMID 25278846, 2014).
papilloma (1 paper, 2019). A benign epithelial neoplasm that projects above the surrounding epithelial surface and consists of villous or arborescent outgrowths of fibrovascular stroma. "Increased susceptibility to papilloma was also observed in the transgenic mice that express IGF1 under keratin-1 or keratin-5 gene promoter." (PMID 30981207, 2019).
PEHO syndrome (1 paper, 2017). PEHO (Progressive encephalopathy with Edema, Hypsarrhythmia and Optic atrophy) syndrome is a rare neurodegenerative disorder belonging to the group of infantile progressive encephalopathies. "In our study, we showed low CSF IGF-1 in patients with progressive cerebellar diseases, including PEHO syndrome and other forms of progressive cerebellar atrophies with severe neurological involvement." (PMID 28954393, 2017). "Our results showed that the levels of IGF-1 in patients with PEHO syndrome were significantly lower than in age-matched controls." (PMID 28954393, 2017).
periapical granuloma (1 paper, 2015). Chronic nonsuppurative inflammation of periapical tissue resulting from irritation following pulp disease or endodontic treatment. "The functional role of EBER in periapical granulomas is unclear; however, it has been demonstrated that EBER induces transcription of cytokines, including IL-10, insulin-like growth factor-1, and IL-9." (PMID 25884725, 2015).
peripheral nerve lesion (1 paper, 2015). "During the repair phase following peripheral nerve lesion, dedifferentiated Schwann cells secrete a variety of neurotrophic factors and cytokines including NGF, BDNF, NT-4/5, FGF-2, IGF-1, IL-6, and IL-1ß that support neuronal survival and regenerative growth of axons." (PMID 26635533, 2015).
phenylketonuria (1 paper, 2023). Phenylketonuria (PKU) is the most common inborn error of amino acid metabolism and is characterized by mild to severe mental disability in untreated patients. "In 2001, a case of a 5-year-old girl heterozygous for a large de novo deletion at 12q23 (involving the IGF1, PAH, and ASCL1 genes) was described, resulting in phenylketonuria." (PMID 37958729, 2023).
pinealoma (1 paper, 2009). "The most important decrease in plasma IGF-1 was observed in patient #19, a female (46 yr-old) with a surgically treated pinealoma." (PMID 19479077, 2009).
Portal vein thrombosis (1 paper, 2014). Thrombosis of the portal vein and/or its tributaries, which include the splenic vein and the superior and inferior mesenteric veins. "Univariate Cox analyses showed thathigh Child-Pugh score, larger tumor size (≥5 cm), multiple tumors (i.e., >1), presence of portal vein thrombosis (PVT), advanced BCLC stage, increasing levels of VEGF, and decreasing levels of IGF-1 were significantly associated with shorter TTP." (PMID 24595361, 2014).
pregnancy disorder (1 paper, 2024). A disorder that is related to pregnancy. "The dysregulation of ID2-mediated IGF-1 signaling in trophoblast cells could be involved in the pathogenesis of pregnancy disorders like uterine growth restriction and PE." (PMID 39768370, 2024).
premature aging syndrome (1 paper, 2018). Changes in the organism associated with senescence, occurring at an accelerated rate. "Low serum IGF-1 has been implicated as a driver of premature aging syndromes." (PMID 29883366, 2018).
PRLomas (1 paper, 2024). "Due to the possibility of mixed secretion of GH and PRL, insulin-like growth factor-1 (IGF-1) assessment is recommended for patients with PRLomas at diagnosis, while its long-term monitoring is not recommended." (PMID 38370355, 2024).